KRAS (KRas proto-oncogene, GTPase)
Diseases named in the same sentence as KRAS in open-access papers (continued):
Sharing a sentence is not in itself a finding about the gene and the disease.
pancreatic cancer (continued). "Moreover, the knockdown of lncRNA-NUTF2P3-001 significantly decreased KRAS expression, proliferation and invasive ability of pancreatic cancer cell both in vitro and in vivo." (PMID 26755660, 2016). "We evaluated whether the combination of the detection of circulating KRAS mutations and the plasma CA19-9 levels could improve the detection of pancreatic cancer." (PMID 27705932, 2016). "The utility of KRAS mutations in plasma circulating cell-free DNA (cfDNA) samples as non-invasive biomarkers for the detection of pancreatic cancer has never been evaluated in a large case-control series." (PMID 27705932, 2016). "Interestingly, we also observed that activation of KRas in mouse pancreatic cancer cells resulted in the increased expression of S100A10." (PMID 27351226, 2016). "Our findings open new avenues for therapeutic intervention in KRAS-mutant cancers, highlighted by the increasing clinical acceptance of therapeutic regimes combining anti-mitotic drugs with other agents for KRAS-mutant lung or pancreatic cancers." (PMID 27412232, 2016). "A previous study of palbociclib in KRAS mutant pancreatic cancer cell lines showed concern that though palbociclib monotherapy inhibited cell proliferation, it appeared to also increase epithelial mesenchymal transition (EMT) in cell lines with wild-type SMAD4." (PMID 27167191, 2016). "We found our conjugate to be effective in KRAS-mutant and KRAS-wildtype pancreatic cancer cells." (PMID 27244881, 2016). "These patient data highlight the potential importance of S100A10 in KRAS-driven pancreatic cancer." (PMID 27351226, 2016). "Acquisition of an oncogenic KRas is a driver mutation for pancreatic cancer, but its downstream signaling has not been fully characterized." (PMID 27649783, 2016). "Furthermore, our findings demonstrate the crucial role of lncRNA-NUTF2P3-001 mediated translational desuppression in KRAS expression and the therapeutic potential of targeting this pathway in pancreatic cancer." (PMID 26755660, 2016). "Mutations in various isoforms of RAS gene, including KRAS are known to upregulate CXC chemokines; however, their precise role in KRAS-driven pancreatic cancer remains unclear." (PMID 26771140, 2016). "In addition, a recent report showed that an engineered ubiquitin ligase suppressed pancreatic cancer cells by targeting mutant KRAS." (PMID 27322423, 2016). "The presence of mutant KRAS in pancreatic cancer correlated with poor prognosis." (PMID 27517148, 2016). "PNA-LNA mediated LAMP was applied for cDNA from 4 kinds of pancreatic carcinoma cell lines with or without KRAS point mutation." (PMID 26999437, 2016). "In addition, pre-treatment with 500 nM BPTES for 48 h did not increase the sensitivities of ß-lap-responsive, NQO1-expressing KRAS wild-type lung, breast, or pancreatic cancer cell lines, consistent with reported literature." (PMID 26462257, 2015). "Downstream effectors of KRAS signaling in pancreatic cancer were widely explored." (PMID 25905463, 2015). "Mutant KRAS is a driving oncogene in the majority of human pancreatic cancer cases." (PMID 26009994, 2015). "The role of KRas in the chemoresistance of pancreatic CSCs still remains to be explored, but a previous study showed that Ras inhibition using farnesylthiosalicylic acid sensitized pancreatic cancer cells to GEM." (PMID 25473894, 2015). "In this context, KRAS may reprogram NSCLC glutamine metabolism similar to that observed in pancreatic cancer to maintain redox balance, thus providing an oncogene driven mechanism of radioresistance." (PMID 26173780, 2015).
pancreatic cancer (continued). "This reduced expression is associated with constitutive activation of MAPK1/ERK2 and, despite the presence of mutated KRAS, exogenous overexpression of DUSP6 induces dephosphorylation of MAPK1/ERK2, subsequent suppression of proliferation, and eventual apoptosis of pancreatic cancer cells." (PMID 25699241, 2015). "Hence, activating mutations of KRAS and BRAF ultimately result in activation of the MAPK signaling pathway, which is crucial for pancreatic cancer." (PMID 25699241, 2015). "A better understanding of the molecular pathways involved in KRAS-driven development and progression of pancreatic cancer could potentially lead to improved targeted therapies." (PMID 25341034, 2014). "It is possible that the regulation of KRAS expression by miR-126 may be restricted to pancreatic cancer cells." (PMID 25245095, 2014). "Furthermore, KRAS and EGFR mutations coexisted in 4 patients (2 patients with pancreatic cancer, 1 with CRC and 1 with NSCLC)." (PMID 25313136, 2014). "In summary, this study demonstrates that RAGE expression is regulated by a NF-κB-dependent pathway and the upregulated binding of RAGE to mutant KRAS facilitates HIF1α activation in a range of pancreatic tumor cells, as well as a spontaneous pancreatic tumor model in transgenic mice." (PMID 25341034, 2014). "Further investigation in mouse models of KRAS driven pancreatic cancer confirmed that combining the AKT inhibitor, GSK2141795 with a MEK inhibitor (GSK2110212; trametinib) resulted in an enhanced anti-tumor effect accompanied with greater reduction in phospho-S6 levels." (PMID 24978597, 2014). "Moreover, we tried to unveil the most relevant molecular pathways involved in KRAS-mediated pancreatic tumor development by taking advantage of transgenic zebrafish reporter lines expressing responsive elements known to be pathway specific." (PMID 24878567, 2014). "Interestingly, in a recent study miR-126 was found to inhibit KRAS expression via a seedless binding site in the KRAS 3'UTR in pancreatic cancer cell lines." (PMID 25245095, 2014). "To characterize phenotypic changes caused by the mutated GNAS in pancreatic ductal cells, we employed HPDE cells (an immortalized cell line derived from healthy pancreatic duct epithelial cells) and pancreatic cancer cell lines (PK-8, PCI-35, and MIA PaCa-2) carrying KRAS mutations." (PMID 24498386, 2014). "However, a disparate viewpoint proposed that Notch-1, as a tumor suppressor in pancreatic cancer, was verified in a model of KRAS-induced PDAC." (PMID 24587996, 2014). "The presence of an activating KRAS mutation has been noted in >90% of pancreatic ductal adenocarcinomas (PDACs), and it is not specific for pancreatic carcinoma." (PMID 25245835, 2014). "Unfortunately, KRAS mutations are not specific to invasive pancreatic cancer and also occur in patients with chronic pancreatitis or in situ neoplasias, or in smokers." (PMID 24084722, 2013). "Oncogenic activation of the KRAS gene occurs in >90% of pancreatic ductal carcinoma and malignant progression from pancreatic intraepithelial carcinoma to a more aggressive form of pancreatic cancer is accompanied by the early acquisition of KRAS oncogene activation." (PMID 23425895, 2013). "Most of the earlier reports on KRAS mutations in pancreatic cancer were based on relatively small tumor numbers that lacked statistical power to determine association with the disease outcome." (PMID 23565280, 2013). "In conclusion, our results show that mutations in KRAS are frequent but not universal in pancreatic tumors and the presence of KRAS mutations in general, and G12D transformation in particular, were indicative of association with poor survival." (PMID 23565280, 2013).
pancreatic cancer (continued). "Additionally, a significantly increased tumor recurrence rate was related to overexpression of KRAS in pancreatic cancers in comparison to that with underexpression (P=0.004)." (PMID 23425895, 2013). "In a recent report, mice expressing activated KRAS and lacking one allele of Pten in the pancreas displayed invasive pancreatic tumors and PI3K/Akt-dependent activation of NF-κB transcription." (PMID 24231729, 2013). "Although KRAS mutations are frequently observed in patients with chronic pancreatitis, not every patient with pancreatitis and KRAS mutations develop pancreatic cancer." (PMID 22615799, 2012). "Interestingly, mutant KRAS stimulates Hedgehog production in pancreatic tumor cells, but seems to reduce their responsiveness to this ligand." (PMID 24213498, 2012). "The diagnostic ability of KRAS is limited by the lack of specificity and sensitivity since mutations can occur in several pathological conditions other than pancreatic cancer." (PMID 22458520, 2012). "This study revealed that in adult mice that expressed an exocrine cell-specific somatic KRAS mutation, PanIN lesions and invasive pancreatic cancer did not develop unless chronic pancreatitis was induced." (PMID 22615799, 2012). "Furthermore, RAS isoforms are the most frequently mutated oncogenes, occurring in approximately 30% of all human cancers, and KRAS is the most commonly mutated RAS gene, with a greater than 90% incidence of mutation in pancreatic cancer." (PMID 21044336, 2010). "Moreover, silencing mutant KRAS by RNA interference (RNAi) in Capan-2 human pancreatic cancer cells resulted in decreased in vivo tumorigenicity." (PMID 21044336, 2010). "Thus, combined the results from both the testing set and patient-derived pancreatic cancer cell lines demonstrate that after treatment persistent cells displays features associated with a senescence-like state in PDAC and suggest KRAS status as a mediator of this process." (PMID 40382842, 2025). "Importantly, our identified HLA-A*11:01–restricted mutant KRAS G12V8–16–reactive TCR–transduced T cells could specifically recognize all tested human pancreatic cancer organoids that expressed HLA-A*11:01 and KRAS G12V, but only killed some of them." (PMID 39846249, 2025). "With respect to pancreatic tumor development, we obtained similar results when we knocked down Ral GTPases, RalBP1 or Sec5 in KRasG12D-expressing acini, highlighting that these Ral-regulated processes are also important in the case of (persistent) ADM initiated by oncogenic KRas mutation." (PMID 40490362, 2025). "Additionally, ADAM9 was shown to stabilize mutant KRAS in pancreatic cancers." (PMID 40429751, 2025). "Interestingly, RNF43 mutations in pancreatic cancer shift the pancreatic cancer dependency to WNT signaling rather than oncogenic KRAS, further underscoring the importance of this E3 ligase as a negative regulator of WNT signaling and a tumor suppressor." (PMID 39851497, 2025). "As we observed KRAS mutations to closely associate with wild-type GNAS IPMN lesions, we decided to use a broader cohort of PDAC cases, not uniquely limited to IPMN, to test whether this association is relevant in a more general context in pancreatic cancer." (PMID 40002298, 2025).
pancreatic cancer (continued). "Importantly, we currently are performing a clinical trial (ClinicalTrials.gov NCT04146298) to evaluate the safety and efficacy of our identified HLA-A*11:01–restricted KRAS G12V8–16–specific TCR in a TCR-gene therapy trial for patients with advanced pancreatic cancer." (PMID 39846249, 2025). "Progress in the development of KRAS inhibitors is particularly crucial because successful implementation of KRAS‐targeted therapy could revolutionize treatment outcomes, especially considering the high malignancy of pancreatic cancers." (PMID 39400496, 2025). "Combining ECT with sotorasib may potentiate antitumor effects in KRAS G12C-mutated pancreatic cancer; however, preclinical data on such combinations are lacking." (PMID 40806294, 2025). "Importantly, we found that induction of KRASG12D expression led to a significant decrease in SIRT3 expression, suggesting that down-regulation of SIRT3 by KRAS might be a mechanism that facilitates KRAS-driven pancreatic cancer development." (PMID 41391757, 2025). "Additionally, given the predominance of KRAS mutation in pancreatic cancer cells, we used a Bcpx3 lacking the KRAS mutation to further evaluate the ferroptosis/necroptosis effect of LA and αLA." (PMID 38388563, 2024). "Moreover, depending on CD47, the modified exosomes could target oncogenic Kirsten rat sarcoma viral oncogene homolog (KRAS) via micropinocytosis, which would suppress pancreatic cancer progression and increase the survival rate in mice models." (PMID 39296981, 2024). "Oncogenic KRAS may maintain pancreatic tumors by regulating anabolic glucose metabolism." (PMID 39588377, 2024). "Furthermore, our TIMER database analysis revealed that ZDHHC20 expression levels were higher in tumor tissues from pancreatic cancer patients harboring KRAS mutations than in those without KRAS mutation." (PMID 38821916, 2024). "Here, we found that FTH1 may be a promising therapeutic target for KRAS-mutant pancreatic cancer." (PMID 39294443, 2024). "Each KRAS mutation allele subtype has unique biochemical and clinicopathological features, and the differences between the mutation subtypes and co-mutations in pancreatic cancer have not been well studied." (PMID 38310130, 2024). "Interestingly, most studies with erlotinib in pancreatic cancer do not distinguish between mutated KRAS and wild-type KRAS populations." (PMID 38607041, 2024). "EGFR mutation has been found to induce synthetic lethality with KRAS mutation in lung adenocarcinoma, which could explain why both mutations do not usually coexist in pancreatic cancer." (PMID 38607041, 2024). "Oncogenic KRAS may maintain pancreatic cancer by regulating anabolic glucose metabolism." (PMID 39588377, 2024). "Similarly, a multicenter study conducted in 2019 revealed a notable disparity in trace element levels between pancreatic cancer patients with and without KRAS (Kirsten rat sarcoma virus) mutation." (PMID 38630209, 2024).
pancreatic cancer (continued). "The identification of lectins that bind predominantly to KRAS mutant organoids compared to KRAS wild-type organoids may contribute to the development of markers that recognize KRAS mutant pancreatic cancer cells and cancer proteins for CTC and hematological diagnosis." (PMID 38528852, 2024). "Glutamine may support the growth of pancreatic cancer through the KRAS-regulated metabolic pathway." (PMID 39588377, 2024). "Therefore, pharmacologically inhibiting oncogenic KRAS signaling has been suggested for a long time and is still considered as the “Holy Grail” in the quest for targeted therapeutic approaches directed against pancreatic cancer by many authors." (PMID 38892436, 2024). "Thus, this study utilized untargeted metabolomic analysis to identify potential biomarkers and elucidate metabolic changes between KRAS-wildtype and -mutant pancreatic cancer cells to gain insights into overcoming treatment challenges in pancreatic cancer management." (PMID 38672219, 2024). "In addition, the ERK inhibitor temuterkib has shown promise in BRAF- and KRAS-mutant pancreatic cancer models, tested alone or in combination with HCQ (NCT04386057), and paricalcitol and HCQ or in combination with GnP (NCT04524702) in advanced or mPDAC patients." (PMID 38495490, 2024). "In KRAS G12D mutant Panc-1 pancreatic cancer cells, neither AMG510 nor Binimetinib treatment alone caused significant reduction of colony growth in soft agar assays, while there was some degree of additive reduction in colony counts upon combined MEK inhibition with irradiation." (PMID 38892436, 2024). "We previously reported that FTH1 is strongly expressed in many KRAS-mutant pancreatic cancer cells; thus, extracellular and intracellular glutamine and glutamate contents were measured to evaluate whether FTH1 is associated with a metabolic shift in glutamine metabolism." (PMID 39294443, 2024). "In addition, chemically modified MIR143 (MIR143#12) anticancer effects involve inhibition of KRAS networks in pancreatic cancer cells with/without KRAS mutation and exhibit high-level RNA nucleases resistance activity." (PMID 37371705, 2023). "The KRAS gene may be an important driver of mitochondrial remodeling in pancreatic cancer." (PMID 36834681, 2023). "For example, in cancers with KRAS-mutant—a key oncogenic driver found in colon, ovary, lung, and pancreas cancers—screening performed using CRISPR nuclease identified synthetic lethal dependencies whose loss cooperates with and sensitizes cancer cells to the inhibition of KRAS pathway effectors." (PMID 37908590, 2023).